KDM4E (lysine demethylase 4E)
Description:
Histone demethylase that demethylates trimethylated 'Lys-9' of histone H3 into monomethylated form, thereby playing a central role in histone code. Also demethylates trimethylated 'Lys-56' of histone H3 (H3K9me3) to generate the monomethylated state (H3K56me1).
Synonyms: KDM4DL; KDM5E; JMJD2E
Tractability: Small molecule: a structure with a bound ligand is known; a high-quality ligand is known; it has a binding pocket of medium quality; it belongs to a druggable protein family. PROTAC: a small molecule that binds it is known.
Target class: Epigenetic regulator; Jumonji domain-containing; Eraser; Lysine demethylase
Chemical probes: IOX1 (high quality)
Gene: Protein-coding gene on chromosome 11 (95,025,258 to 95,027,596, forward strand). Ensembl gene ENSG00000235268.
Subcellular location: Nucleus
Pathways (Reactome):
Developmental Biology: Zygotic genome activation (ZGA)
Gene Ontology:
Molecular function: histone H3K56me2/H3K56me3 demethylase activity; histone H3K9me2/H3K9me3 demethylase activity; histone H3K9 demethylase activity
Biological process: chromatin remodeling
Cellular component: nucleus; chromatin; nucleoplasm
Genetic constraint (gnomAD): Missense variants: 576 observed, 611.44 expected, observed/expected ratio (o/e) 0.94, 90% interval 0.88 to 1.01. Synonymous variants: 229 observed, 215.82 expected, observed/expected ratio (o/e) 1.06, 90% interval 0.95 to 1.18.
Homologues: Orthologues: chimpanzee KDM4E (98% identical), macaque KDM4E (88% identical), zebrafish kdm4c (47% identical), Drosophila melanogaster Kdm5 (23% identical), Caenorhabditis elegans rbr-2 (21% identical). Paralogues in human: KDM4F (83% identical), KDM4D (66% identical), KDM4B (53% identical), KDM4C (49% identical), KDM4A (49% identical), KDM5B (25% identical), KDM5A (25% identical), KDM5C (25% identical), KDM5D (25% identical), JARID2 (18% identical).
Diseases named in the same sentence as KDM4E in open-access papers:
KDM4E is named in the same sentence as 6 diseases in open-access papers, as found by Europe PMC text mining. Sharing a sentence is not in itself a finding about the gene and the disease. The quoted sentences say what the papers report.
infarction (1 paper, 2022). A localised pathological necrosis of tissue resulting from obstruction of the blood supply usually by a thrombus, an embolus, or vascular torsion. "An important point is to determine whether KDM4E-mediated H3K9me3 loss influences the adaptation and cardioprotection of ADSCs implanted into the high BCAA milieu seen in the post-infarction heart." (PMID 35654769, 2022).
non-small cell lung carcinoma (1 paper, 2021). A group of at least three distinct histological types of lung cancer, including non-small cell squamous cell carcinoma, adenocarcinoma, and large cell carcinoma. "The most advanced preclinical KDM4 inhibitor is JIB-04 which targets KDM4A, KDM4B, and KDM4E and can inhibit growth and reduce tumor burden in non-small cell lung cancer (NSCLC) and breast cancer in vitro and in vivo." (PMID 34220955, 2021).
cancer (4 papers, 2020 to 2022). A tumor composed of atypical neoplastic, often pleomorphic cells that invade other tissues. "On the other hand, until recently, KDM4E was considered a pseudogene due to its low expression levels; however, recent reports point out that it encodes an active enzyme involved in H3K9me3 demethylation; nevertheless, KDM4E’s role in cancer has not been explored yet." (PMID 35480330, 2022).
tumor (3 papers, 2022 to 2024). "ML324 is a different KDM4 inhibitor in the arsenal; it specifically targeted KDM4B and KDM4E, suppressed prostate cancer proliferation both in vitro and in vivo, and decreased tumor volume and growth in a triple-negative breast cancer mice model." (PMID 37218871, 2023). "JIB-04, the most advanced preclinical KDM4 inhibitor, inhibits growth and lowers tumor burden in non-small cell lung cancer and breast cancer, both in vitro and animals, and targets KDM4A, KDM4B, and KDM4E." (PMID 37218871, 2023).
KDM4E also shares sentences with these, for which no sentence is quoted: lung adenocarcinoma (1 paper); neuroblastoma (1).